ELAVL1 (ELAV like RNA binding protein 1)
Diseases named in the same sentence as ELAVL1 in open-access papers (continued):
Sharing a sentence is not in itself a finding about the gene and the disease.
prostate carcinoma (27 papers, 2009 to 2025). A carcinoma that arises from epithelial cells of the prostate gland. "ELAVL1 is highly expressed in prostate cancer and contributes to tumor progression, chemoresistance, and radioresistance." (PMID 40958880, 2025). "In summary, ELAVL1-targeted therapy using nanodelivery systems represents a promising new approach for the treatment of prostate cancer." (PMID 40958880, 2025). "In contrast, ELAVL1-targeting systems can achieve tumor-specific delivery by exploiting the overexpression and cytoplasmic translocation of ELAVL1 in prostate cancer cells." (PMID 40958880, 2025). "Silencing ELAVL1 expression effectively inhibits the proliferation, invasion, and metastasis of prostate cancer cells." (PMID 40958880, 2025). "siRNA-mediated suppression of ELAVL1 effectively inhibits prostate cancer cell growth and viability, positioning siRNA as a powerful therapeutic tool because of its high specificity and tunability." (PMID 40958880, 2025). "For instance, ELAVL1 has been found to be highly expressed in prostate cancer, and it thus acts as an independent predictor positively correlating with tumor staging and metastasis." (PMID 35465324, 2022). "ELAVL1 promotes cell proliferation and migration of cells of the prostate cancer lines LNCaP and PC-3 by targeting vascular endothelial growth factors A and C and COX-2." (PMID 35465324, 2022). "Enforced expression of the miR-34a precursor into paclitaxel resistant prostate cancer cells resulted in decreases in ELAVL1." (PMID 24739220, 2014). "In our study, ELAVL1 was found to be highly expressed in prostate cancer." (PMID 35978821, 2022). "Knockdown of ELAVL1 can inhibit the proliferation of prostate cancer." (PMID 35978821, 2022). "It has been suggested that ELAVL1 is an RNA-binding protein, which may play a translational modification regulatory sway in prostate cancer progression." (PMID 35711911, 2022). "METTL3 stabilizes ARHGDIA mRNA by modulating ELAVL1 expression in prostate cancer." (PMID 36348434, 2022). "Therefore, it is understandable that miRNA mediated control of AR is lost in TMPRSS2-ERG positive prostate cancer and ELAVL1 stabilizes the expression of AR and ERBB2 which synchronously trigger the expression of cancer promoting genes." (PMID 24739220, 2014). "HuR (also known as ELAV Like RNA Binding Protein 1) interacts with this modified mRNA to increase its stability and promote protein expression, making prostate cancer cells capable of adhering to collagen I in bone marrow stroma." (PMID 32765970, 2020). "ELAVL1 (HuR) is an RNA-binding protein and the decreased of ELAVL1 can resist cell proliferation and invasion in ovarian and prostate cancer." (PMID 27764782, 2016). "Owing to the high protein sequence homology between ELAVL1 and ELAVL3, we reasonably expected that PP may inhibit the function of ELAVL3, thereby impeding the neuroendocrine differentiation of prostate cancer cells." (PMID 38016952, 2023). "A detailed mechanistic investigation indicated that specific binding of the RNA binding protein- ELAV (embryonic lethal, abnormal vision, Drosophila)-like 1 (Hu antigen R) (HuR; ELAVL1) to this U-rich element momentously enhanced ERBB2 expression in prostate cancer cells." (PMID 24739220, 2014). "In prostate cancer, METTL3 improves the YTHDF2–HNRNPD-recognized degradation of ubiquitin-specific peptidase 4 (USP4) by mediating m6A modification on A2696 and then maintains the ubiquitin of ELAV-like RNA-binding protein 1 (ELAVL1), giving rise to the migration and invasion of cancer cells." (PMID 35804965, 2022). "Besides, m6A modification mediates the biogenesis of circDDIT4, which binds to ELAVL1 and acts as an RBP sponge to downregulate the expression of ELAVL1 target mRNAs, including ANO7, thus exerting a tumor suppressor effect on the progression of prostate cancer." (PMID 40830264, 2025).
liver cancer (24 papers, 2011 to 2025). An epithelial or non-epithelial malignant neoplasm that arises from the liver. "Moreover, high ELAVL1 mRNA expression applied to all liver cancer stages and was associated with poorer patient survival." (PMID 38507413, 2024). "Altogether, we corroborate that ELAVL1 expression and SUMO dynamics are decompensated in human liver cancer tumors, which led us to describe that HuR is SUMOylated in HCC mouse and human cell line models and, more importantly, in patients." (PMID 38507413, 2024). "For example, in liver cancer, it enhances malignant phenotypes through the miR-33a-5p/ELAVL1 axis." (PMID 40644833, 2025).
bladder cancer (22 papers, 2013 to 2026). "HuR, also known as ELAVL1, is an RNA‐binding protein, in which lncHCG22 inhibits bladder cancer progression by destabilising HuR proteins to regulate PTBP1 levels." (PMID 40579921, 2025). "For example, m5C reader Y-box binding protein 1 can recruit ELAV-like RNA binding protein 1 (ELAVL1) in bladder cancer (BLCA), thus increasing the stability of hepatoma-derived growth factor (HDGF) mRNA and promoting the invasion of BLCA cells." (PMID 37769000, 2023). "Our findings contradict those of previous studies that reported the direct or indirect inhibitory effect of PP on cytoplasmic accumulation of ELAVL1 in bladder cancer cells." (PMID 38016952, 2023). "The m5C recognition protein YBX1 recognizes m5C-modified mRNA through the W65 indole ring in its cold shock domain and subsequently recruits ELAV like protein 1 (ELAVL1) to stabilize heparin-binding growth factor mRNA, which ultimately promotes bladder cancer cell proliferation and metastasis." (PMID 41326692, 2026). "In addition, the pathogenesis of bladder cancer is promoted by recruiting ELAVL1 to stabilize target mRNAs." (PMID 35276059, 2022). "The reduction in USP4 expression decreases the level of ELAVL1 protein deubiquitination, leading to decreased ELAVL1 protein expression and increased ARHGDIA expression, promoting bladder cancer cell migration and invasion." (PMID 37996892, 2023). "It was found in humans and animal models that METTL3, FTO, IGF2BP1, IGF2BP3, YTHDF1, YTHDF 2, ELAV-like protein 1 (ELAVL1), HNRNPA2B1 were upregulated in bladder cancer cells." (PMID 37701836, 2023). "YBX1 binds to HDGF mRNA in an m5C-depend manner, and ELAVL1 mediates the half-life of HDGF mRNA by interacting with YBX1, promoting bladder cancer pathogenesis." (PMID 36348434, 2022). "In bladder cancer, the cytoplasmic protein YBX1 recognizes the NSUN2-dependent m5C site located on the 3'UTR of heparin-binding growth factor (HDGF) mRNA and recruits ELAV-like RNA-binding protein 1 (ELAV1) to improve its stability." (PMID 35562754, 2022). "In bladder cancer, Y-Box Binding Protein 1 (YBX1) has been identified as a an m5C “reader” and was shown to promote carcinogenesis by stabilizing Hepatoma-Derived Growth Factor (HDGF) through an interaction with Elav-Like RNA-Binding Protein 1 (ELAVL1)." (PMID 32708015, 2020).
atherosclerosis (21 papers, 2018 to 2024). A disease characterized by the build-up of fatty material and calcium deposition in the arterial wall resulting in partial or complete occlusion of the arterial lumen. "The expression of Elavl1 was increased in the progressive atherosclerosis compared with that in the regressive atherosclerosis." (PMID 35211628, 2022). "Of interest, ELAVL1 has emerged as an important target of a macrophage-specific long non-coding RNA that contributes to the process of atherosclerosis." (PMID 34760935, 2021). "Together with recent work tying ELAVL1 in mediating the pro-atherosclerosis effect of a macrophage-specific lncRNA, these studies point to an interesting parallel that may contribute to arterial calcification mediated through ELAVL1 modulation of IRF2BP2." (PMID 34760935, 2021). "HuR, also known as ELAVL1, is a widely expressed RNA-binding protein that stabilizes its mRNA targets and may promote atherosclerosis occurrence and development." (PMID 34015766, 2021). "Using RNA sequencing profiling of the aortic intima of lesions, the authors identified a macrophage-specific lncRNA, Macrophage-Associated Atherosclerosis lncRNA Sequence (MAARS), that regulates apoptosis and efferocytosis in atherosclerosis by tethering ELAV like RNA binding protein 1 (ELAVL1) HuR." (PMID 34084771, 2021). "Mechanistic studies have verified that AK136714 directly targets HuR (ELAVL1) to promote the mRNA stability of TNF-α and IL-1β and increases the transcription of Bim, indicating that AK136714 could function in atherosclerosis and provide potential novel drug targets for atherosclerosis intervention." (PMID 37418054, 2024).
glioblastoma (21 papers, 2008 to 2025). The most malignant astrocytic tumor (WHO grade IV). "In glioblastoma, pyruvate kinase M2, which is up-regulated, binds to ELAVL1 and promotes its cytoplasmic localization, prompting tumor cells to enter a dividing state and promoting cell growth." (PMID 35465324, 2022). "In a nude mouse model of glioblastoma, knockdown of ELAVL1 reduced tumor growth and proliferation, and prolonged survival time." (PMID 35465324, 2022). "In glioblastoma multiforme and adjacent tissues, high expression of ELAVL1 can also be detected." (PMID 35465324, 2022).
diabetes (16 papers, 2018 to 2025). "Numerous different RBPs are implicated in diabetes, including TAR DNA-binding protein, ELAVL1, LIN28a and RBFOX2." (PMID 40243689, 2025). "However, chronic ELAVL1 activation in diabetes sustains pro-apoptotic UPR pathways, contributing to cardiomyocyte loss." (PMID 40243689, 2025). "In addition, the promoting effects of the miR-30e-5p inhibitor on IL-1β and IL-18 expression were dramatically reversed by ELAVL1 knockdown in the BMSC-exo-treated diabetes model cells." (PMID 36794663, 2023). "Additionally, Human Antigen R (HuR) also known with its alternative name ELAVL1, is a ubiquitously expressed RBP, which is upregulated and activated under high glucose and in diabetes." (PMID 33923168, 2021).
melanoma (16 papers, 2008 to 2025). A malignant, usually aggressive tumor composed of atypical, neoplastic melanocytes. "Our previous research revealed that LINC1392 regulates melanoma differentiation-associated gene 5 (MDA5) by interacting with ELAV-like RNA-binding protein 1 (ELAVL1), inhibiting CVB5 infection." (PMID 40626722, 2025). "Previously, our lab identified two lncRNAs involved in the IFN-I pathways, such as LINC1392, which regulated the melanoma differentiation-associated gene 5 (MDA5) by interaction with ELAV-like RNA binding protein 1 (ELAVL1) to inhibit CVB5 infection." (PMID 40626722, 2025). "In fact, ELAVL1 knockdown led to suppression of the proliferation of melanoma cells with mutated BRAF (V600E), which is consistent with our results that ELAVL1 is a sensitive SP for mutated BRAF." (PMID 34681774, 2021). "In our study, we found that ELAVL1 was not only associated with metastasis of melanoma, but also reflected a poorer prognosis of patients, which may be related to the fact that ELAVL1 can stabilize oncogenic transcripts." (PMID 34993195, 2021). "This concurs with findings that the TRAF2/PIAS2/ELAVL1/EPHA5 pathway is pivotal in IL-17A-induced melanoma." (PMID 40809015, 2025). "IL-17 also induces EPHA5 via TRAF2 to recruit PIAS2 and ELAVL1 to promote melanoma development." (PMID 39906741, 2024). "Induces EPHA5 via TRAF2 to recruit PIAS2 and ELAVL1 to promote melanoma development." (PMID 39906741, 2024). "IL-17A stimulation recruits ELAVL1 and PIAS2 via TRAF2, stabilizing EPHA5 mRNA and promoting melanoma cell proliferation and invasion." (PMID 40809015, 2025). "Comparing primary melanoma and metastases, we found that ALKBH5, ELAVL1, FMR1, HNRNPA2B1, HNRNPC, IGF2BP1/2/3, KIAA1429, LRPPRC, RBM15, YTHDC1/2, YTHDF1/3, and ZC3H13 were significantly upregulated in metastases, while RBM15B and METTL3 were significantly upregulated in primary melanoma." (PMID 34993195, 2021). "The role of ABCF1 in melanoma has not been reported, but in our PPI analysis, we found that ABCF1 was indirectly correlated with ELAVL1, which may be the mechanism how it participates in melanoma progress." (PMID 35722625, 2022).
triple-negative breast carcinoma (16 papers, 2013 to 2025). An invasive breast carcinoma which is negative for expression of estrogen receptor (ER), progesterone receptor (PR), and human epidermal growth factor receptor 2 (HER2). "ELAVL1 (EP: 0.0016, t-test p-value: 0.805) was found to be modulated by MUC16, which promotes triple-negative breast cancer lung metastasis." (PMID 37761960, 2023). "From all the RBPs investigated, seven were differentially expressed and upregulated (AGO2, EIF4A3, ELAVL1, IGF2BP2/3, LIN28B, and U2AF2), showing that these genes have an important role in triple-negative breast cancer development." (PMID 35805051, 2022).
diabetic nephropathy (14 papers, 2017 to 2025). "In diabetic nephropathy, ELAVL1 expression exhibits abnormalities and is considered an independent risk factor for kidney disease progression." (PMID 39359249, 2024). "Upregulation of ELAVL1 may promote HG-induced glomerular mesangial cell injury by stabilizing NADPH oxidase four during the course of diabetic nephropathy (Chen HY." (PMID 39359249, 2024). "Moreover, lncRNA MALAT1 modulates renal tubular epithelial pyroptosis in diabetic nephropathy via sponging miR-23c and targeting ELAVL1." (PMID 32370736, 2020).
non-small cell lung carcinoma (14 papers, 2013 to 2025). A group of at least three distinct histological types of lung cancer, including non-small cell squamous cell carcinoma, adenocarcinoma, and large cell carcinoma. "ELAVL-1/HuR has been shown to modify tumor growth in non-small cell lung carcinoma and cigarette smoke induced associated airway inflammation." (PMID 28196122, 2017).
breast tumor (13 papers, 2010 to 2024). "Accordingly, in breast tumors, enhanced ELAVL1 levels correlate with an increase in both GAC mRNA levels and KGA mRNA levels." (PMID 38965208, 2024). "Transcriptomic evaluation of TCGA breast tumor samples with high versus low ELAVL1 levels revealed that several genes from the glucose, TCA, fatty acid synthesis, beta-oxidation, and urea cycle pathways had altered expression levels." (PMID 38965208, 2024). "The ELAVL1 (the gene that encodes HuR) and CCL20 expression levels were both markedly increased in breast tumor tissues compared with normal breast tissues." (PMID 28851919, 2017).
pulmonary fibrosis (11 papers, 2021 to 2025). Chronic progressive interstitial lung disorder characterized by the replacement of the lung tissue by connective tissue, leading to progressive dyspnea, respiratory failure, or right heart failure. "Recent findings indicate that activating transcription factor 3 (ATF3) can stimulate LINC00941/lncIAPF to promote the differentiation of fibroblasts into myoblasts by inhibiting ELAVL1/HuR-dependent autophagy in pulmonary fibrosis." (PMID 39612365, 2024).
thyroid cancer (11 papers, 2016 to 2025). "In thyroid cancer, NPSR1-AS1 promotes malignant behavior by stabilizing NPSR1 mRNA through interaction with the RNA-binding protein ELAVL1 (ELAV Like RNA Binding Protein 1), leading to MAPK (Mitogen-activated protein kinase) pathway activation." (PMID 40724881, 2025).
Insulin resistance (10 papers, 2018 to 2026). Increased resistance towards insulin, that is, diminished effectiveness of insulin in reducing blood glucose levels. "The ELAVL1 gene in MDD patients was also found to be enriched in pathways such as cellular senescence, adipocytokine signaling pathway, glucagon signaling pathway, and insulin resistance, indicating its association with metabolic disorders in depressive patients." (PMID 38714976, 2024).
oral cancer (10 papers, 2009 to 2023). "However, a recent study reported RNA—dependent direct physical interaction between ELAVL1 and hnRNPD in the nucleus influences the expression of cyclin D1 and p16, both of which are important for oral cancer development." (PMID 26318153, 2015). "In addition, our results also suggested interaction of hnRNPD with other RNA binding proteins (RBPs) such as ELAVL1, RALY, EWSR1 and FUS in oral cancer." (PMID 26318153, 2015).
pancreatic ductal adenocarcinoma (10 papers, 2015 to 2025). An infiltrating adenocarcinoma that arises from the epithelial cells of the pancreas. "Moreover, ELAVL1 might stabilize mRNA of yes‐associated protein 1 to regulate pancreatic ductal adenocarcinoma cell migration." (PMID 39588852, 2025). "Human Antigen R (HuR/ELAVL1) is known to regulate stability of mRNAs involved in pancreatic ductal adenocarcinoma (PDAC) cell survival." (PMID 35406624, 2022). "Pancreatic ductal adenocarcinoma cells expressing pro-oncogenic mRNA stability factor HuR (ELAVL1) show sensitization to oxaliplatin and 5-fluorouracil through persistent PARylation." (PMID 32344695, 2020). "We have previously shown that the mRNA-binding protein HuR (ELAVL1) is elevated in human pancreatic ductal adenocarcinoma (PDA) specimens compared to normal pancreatic tissues, and its cytoplasmic localization is associated with increased tumor stage." (PMID 26314962, 2015).
Hyperglycemia (9 papers, 2017 to 2025). An increased concentration of glucose in the blood. "ELAVL1 plays an important role in inhibiting hyperglycemia-induced cardiomyocyte pyroptosis and regulating ferroptosis in myocardial injury." (PMID 35207515, 2022). "MiRNA-9 inhibits the pyroptosis induced by hyperglycemia through targeting ELAVL1 in human ventricular cardiomyocytes." (PMID 32370736, 2020). "miR-9 mimics attenuated hyperglycemia-induced ELAV-like protein 1 (ELAVL1) and inhibited cardiomyocyte apoptosis." (PMID 29204251, 2017). "miR-23c, as a target of lncRNA MALAT1, could directly repress its target ELAVL1 and inhibit hyperglycemia-induced cell pyroptosis." (PMID 31481972, 2019).
liver diseases (9 papers, 2020 to 2025). "Embryonic lethal abnormal vision like 1 (ELAVL1) is an RBP that plays a key role in the development of liver disease." (PMID 39990675, 2025). "From the perspective of background liver disease, the ELAVL1 positivity rates in HBV-related HCC (93.8%) are higher than those in HCV-related (89.3%) and non-viral HCC (90.9%)." (PMID 35887229, 2022). "The role of ELAVL1 as an RBP in liver disease has been gradually revealed." (PMID 39990675, 2025).
viral infection (9 papers, 2011 to 2025). "Previous studies have found that the ELAVL1 gene is associated with susceptibility to human coronavirus infection, indicating the biological mechanism of m6A methylation mediated by the ELAVL1 gene in the process of virus infection in MDD patients." (PMID 38714976, 2024). "Therefore, it is evident that ELAVL1 and YTHDC2 genes may be associated with the m6A methylation process in MDD through virus infection pathways." (PMID 38714976, 2024). "A viral infection is envisioned to interact with predisposition networks which include counterpart proteins in various downstream stages (including in the current data set: FOS, ELAVL1, NFkB1, POLR3B, and others at different cellular compartments and stages of the tumorigenesis)." (PMID 26442106, 2015).